RN7SL714P (RNA, 7SL, cytoplasmic 714, pseudogene)
Gene: Miscellaneous RNA gene on chromosome 14 (98,351,367 to 98,351,664, reverse strand). Ensembl gene ENSG00000241757.
Homologues: Orthologues: chimpanzee Metazoa_SRP (99% identical), macaque Metazoa_SRP (92% identical). Paralogues in human: RN7SL1 (84% identical), RN7SL126P (83% identical), RN7SL2 (83% identical), RN7SL3 (83% identical), RN7SL113P (82% identical), RN7SL296P (82% identical), RN7SL788P (82% identical), Metazoa_SRP (82% identical), RN7SL627P (82% identical), RN7SL620P (81% identical), RN7SL664P (81% identical), RN7SL786P (81% identical), and 701 more.